GSK3B (glycogen synthase kinase 3 beta)
Diseases named in the same sentence as GSK3B in open-access papers (continued):
Sharing a sentence is not in itself a finding about the gene and the disease.
lymphoma (20 papers, 2015 to 2025). A malignant (clonal) proliferation of B- lymphocytes or T- lymphocytes which involves the lymph nodes, bone marrow and/or extranodal sites. "In line with our results, the activation of GSK3β has been previously implicated in glucocorticoid-induced apoptosis in lymphoma cells, its inactivation resulting in glucocorticoid resistance, although effects on inflammatory responses were not studied." (PMID 26320152, 2015). "Over the past decade, GSK-3β has emerged as a therapeutic target in several different types of cancer, including lymphoma." (PMID 41220107, 2025). "To confirm the importance of its action on GSK3β, we treated 3 lymphoma cell lines with selective, structurally distinct GSK3 inhibitors: CT99021, SB216763, LY2090314, tideglusib, and elraglusib." (PMID 37316860, 2023). "Either GSK-3β genetic knockdown or chemical inhibition by CHIR99021 rescues the proliferative capability of BCR- lymphoma cells to levels similar to those of BCR+ cells." (PMID 35681507, 2022). "More importantly, either deletion of the GSK-3β gene through CRISPR-Cas9 technology or GSK-3β knockdown by shRNA leads to lymphoma cell growth arrest at the G2/M phase of the cell cycle." (PMID 35681507, 2022). "As expected, BCR- lymphoma cells show decreased levels of GSK-3β phosphorylated on Ser9 through PI3Kδ/phosphoinositide-dependent kinase 1 (PDK1)/Akt signaling." (PMID 35681507, 2022). "Recently it has been demonstrated that genetic depletion or pharmacologic inhibition of GSK-3β by 9-ING-41 induced cell cycle arrest at G2/M in lymphoma cells." (PMID 31882719, 2019). "Herein, we explore mechanisms of anti-lymphoma activity of the GSK-3β inhibitor 9-ING-41 and address the feasibility of targeting GSK-3β in lymphoma as a single agent." (PMID 29383130, 2017). "In addition, GSK-3β was important in MYC-driven lymphomagenesis and inhibitors targeting GSK-3β played an inhibitory role in many lymphomas." (PMID 39588389, 2024). "Although a prior study suggested that indirect inhibition of MYC degradation by targeting glycogen synthase kinase 3β (GSK-3β) can increase doxorubicin sensitivity, others have shown that translation inhibition in chemoresistant lymphomas restores sensitivity to doxorubicin." (PMID 37768948, 2023). "However, the molecular mechanisms underlying this effect are still awaiting clarification, although GSK-3β has been shown to bind to centrosomes and mitotic spindles in lymphoma cells." (PMID 35681507, 2022). "Venetoclax or BAY-1143572 in relevant lymphoma cell lines may be minimal but contend that our data support the need for ongoing investigation of GSK-3β as a therapeutic target in single and combinatorial strategies." (PMID 29383130, 2017). "Thus, GSK3B inhibitors are currently used to target different acute leukemia and lymphoma forms." (PMID 29674676, 2018). "Studies have shown that GSK-3β is directly involved in cell death induced by PI3K/mTOR inhibitors and panhistone deacetylase inhibitors in lymphoma cell lines." (PMID 40643495, 2025). "In lymphoma cells, PRMT5 activates the WNT/β-catenin and AKT/GSK3β signaling pathways and regulates target gene expression." (PMID 36765032, 2023). "We report a case of adult T-cell leukemia/lymphoma (ATLL) treated with 9-ING-41, a selective GSK-3β inhibitor in clinical development, who achieved a durable response." (PMID 35815408, 2022). "Researchers have investigated the relationship between PRMT5 and Wnt/β-catenin signalling as well as AKT/GSK3β proliferative signalling in three different types of NHL cell lines, clinical samples, and mouse primary lymphoma cells." (PMID 36224652, 2022). "In patient-derived lymphoma cell lines, activated AKT phosphorylates GSK3β Ser9 which results in the inactivation of GSK-3β, which elevated p-β-catenin (Ser-675)." (PMID 34503515, 2021). "Phosphorylation of GSK3β by AKT inactivates GSK3β kinase activity, and this inhibition is necessary for the fitness of MYC-driven lymphoma cells." (PMID 31645904, 2019).
lymphoma (continued). "In contrast, the divergence in expression observed for GSK3B and PIK3CD between lymphomas and cell lines is likely due to clonal selection or cultivation induced artifacts, hence limiting the value of the cell lines as drug testing system." (PMID 29674676, 2018). "In this study, we explored the anti-tumor effects of the GSK-3β inhibitor, 9-ING-41, in lymphoma cell lines as a single agent and in combination with novel agents comprising BCL-2 inhibitor (Venetoclax), CDK-9 inhibitor (BAY-1143572) and p110δ-PI3K inhibitor (Idelalisib)." (PMID 29383130, 2017). "We observed that BUD was not able to restore epithelial barrier dysfunction upon pharmacological inhibition of GSK-3β, indicating that GSK-3β activation is indispensable for the responsiveness of the epithelial barrier to BUD, in line with previous findings in lymphoma cells." (PMID 26739349, 2016). "Furthermore, as seen in the EL4 lymphoma model, a significant decrease in Pdcd1 gene expression was also seen in the Gsk3b cKO but not in Gsk3a cKO cells." (PMID 34142056, 2021).
amyotrophic lateral sclerosis (19 papers, 2011 to 2025). Amyotrophic lateral sclerosis (ALS) is a neurodegenerative disease characterized by progressive muscular paralysis reflecting degeneration of motor neurons in the primary motor cortex, corticospinal tracts, brainstem and spinal cord. "Amyotrophic lateral sclerosis (ALS)-linked protein TDP-43 disrupts MAMs by impairing the VAPB–PTPIP51 complex via activation of glycogen synthase kinase-3β (GSK3β)." (PMID 41367495, 2025). "GSK-3β has recently been identified as one of the important pathogenic mechanisms in motor neuronal death related to amyotrophic lateral sclerosis (ALS)." (PMID 21603026, 2011). "GSK3β inhibition has emerged as a potential therapeutic approach in amyotrophic lateral sclerosis models by rescuing disease-relevant phenotype, thus enhancing neuronal survival." (PMID 40988055, 2025). "Amyotrophic lateral sclerosis (ALS) is a neurodegenerative disease of motor neurons, motor cortex, and corticospinal tract linked with GSK-3β overactivity." (PMID 38367137, 2024). "Glycogen synthase kinase-3β (GSK-3β) inhibitors have been suggested as a core regulator of apoptosis and have been investigated as therapeutic agents for neurodegenerative diseases, including amyotrophic lateral sclerosis." (PMID 29082245, 2017). "Two proteins, namely fused in sarcoma (FUS) and TAR DNA binding protein-43 (TDP-43), are known to induce hyperactivation of GSK-3β and lead to amyotrophic lateral sclerosis (ALS)." (PMID 40148800, 2025). "GSK-3β was also reported to be associated with amyotrophic lateral sclerosis (ALS), elevated levels of active GSK-3β were found in the brain of ALS patients." (PMID 35163631, 2022). "The regulation of VAPB-PTPIP51 in amyotrophic lateral sclerosis and frontotemporal dementia (ALS/FTD) by FUS metabolism defects through GSK3β mediated regulation of complex formation and supports disease development." (PMID 38434478, 2024). "Tideglusib, a selective non-ATP-competitive GSK-3β inhibitor, has been applied in clinical trials for several neurological diseases, including AD, myotonic dystrophy type 1, progressive supranuclear palsy, and amyotrophic lateral sclerosis." (PMID 38684682, 2024).
atherosclerosis (19 papers, 2014 to 2025). A disease characterized by the build-up of fatty material and calcium deposition in the arterial wall resulting in partial or complete occlusion of the arterial lumen. "Moreover, HSV1, connected to both atherosclerosis and AD, was demonstrated to invade ECs, activating glycogen synthase kinase 3 beta (GSK3β), an enzyme previously associated with neurodegeneration." (PMID 31297054, 2019). "Conversely, USP14 deficiency regulates the posttranslational modifications of scavenger receptor CD36 to suppress atherosclerosis development and cardiac hypertrophy by regulating GSK-3β phosphorylation and mediates lipopolysaccharide-induced inflammation." (PMID 38909015, 2024). "This suggests that endothelial/macrophage GSK3α is an important contributor to plaque accumulation, and supports previous findings that GSK3α and GSK3β display different functional roles in the context of atherosclerosis." (PMID 36499109, 2022). "Moreover, in atherosclerosis-prone apolipoprotein E (ApoE) KO mice, increased GSK3β serine phosphorylation (presumably including Ser9) was observed at atherosclerotic lesions." (PMID 39125833, 2024). "The 6 ingredients were highly related to arteriosclerotic cardiovascular disease and atherosclerosis and could mainly interact with similar targets, e.g., GSK3B, PDPK1, PLAU, etc., or pathways, e.g., Insulin, VEGF, FoxO, etc, providing the basis for integrating plasma drug concentration." (PMID 32922299, 2020). "GSK3β is a well-studied isoform of GSK3, which has been found to be involved in a wide range of diseases, including metabolic diseases, inflammatory diseases, neurological disorders, cancer, and atherosclerosis." (PMID 40143103, 2025). "Results from our lab suggest that myeloid deletion of GSK3α, but not GSK3β, attenuates the progression of atherosclerosis." (PMID 36012557, 2022). "The PI3K-Akt signaling pathway is involved in atherosclerosis by blocking blood flow and inhibiting the migration of fibroblasts and can suppress neuronal cell death and improve tau hyperphosphorylation by BCL2, GSK3B, and IGF1R." (PMID 32802132, 2020).
multiple myeloma (19 papers, 2007 to 2026). "PI3K/Akt/GSK3β signaling crosstalks with Hsp70/Hsp90 expression by inducing HSF1 expression in multiple myeloma." (PMID 39936995, 2025). "In hematological tumors (multiple myeloma), LiCl triggers cell cycle arrest and apoptosis by inhibition of GSK3β and the activation of the Wnt/β-catenin signaling pathway." (PMID 36836894, 2023). "LiCl inhibits multiple-myeloma proliferation in a dose-dependent manner and triggers cell cycle arrest and apoptosis through inhibition of GSK3β, which is a crucial mediator of the Wnt/β-catenin pathway." (PMID 36836894, 2023). "RRM2 silencing has been suggested to inactivate the Wnt/β-catenin signaling pathway by increasing GSK-3β phosphorylation in multiple myeloma." (PMID 35609318, 2022). "Thus, we took western blot experiments to test the expression levels of PTEN, AKT, p‐AKT, GSK3β, p‐GSK3β, and cyclinD1 in the osteoblasts from ten myeloma patients." (PMID 31769620, 2020). "Increasing Wnt signalling in the bone microenvironment in multiple myeloma with anti-DKK1 antibody or inhibition of glycogen synthase kinase-3β (GSK-3β) with lithium chloride resulted in the inhibition of myeloma bone disease as shown in a murine model of myeloma." (PMID 29535427, 2018). "In this study, we have investigated GSK-3α and GSK-3β function in multiple myeloma (MM)." (PMID 20920357, 2010). "The mononuclear cells from AL amyloidosis patients had lower expression levels than the cells from myeloma patients for BDNF, calmodulin, phospho‐TBK1, and phospho‐ULK1 in CD4+ T cells and phospho‐GSK3β in monocytes, but higher levels of HO1 in monocytes." (PMID 40977494, 2025). "This is confirmed by the combined treatment of LiCl, the inhibitor of GSK3β, and Dex, a major anti-MM agent, which strikingly upregulate HERC4 and inhibit MafA therefore suppressing MM cell proliferation and myeloma xenograft growth in mice." (PMID 37028761, 2023). "In multiple myeloma, AT7519 induces rapid dephosphorylation of GSK-3β at Ser9, leading to in vitro apoptosis and in vivo antitumor activity, which prolongs survival." (PMID 35698192, 2022). "As in the myeloma patients samples, several protein pots including PTEN, GSK3β, and 4E‐BP1 in the array had been observed have involvements." (PMID 31769620, 2020). "Inhibition of GSK3β by thiadiazolidinone (TDZD) in MM.1, U266, and other myeloma cells resulted in the inhibition of cell proliferation and induction of apoptosis via the dephosphorylation and activation of FOXO3a as well as increase of FasL and IκBα levels." (PMID 26560046, 2015). "In the present study, we found that inhibition of GSK3β and induction of HERC4 might inhibit MafA and suppress myeloma cell proliferation and tumor growth." (PMID 37028761, 2023). "In multiple myeloma cells, re-expression of PCDH10 suppressed nuclear localization of β-catenin, activity of LEF/TCF, expression of the β-catenin transcriptional cofactor BCL9, and of AKT, whereas expression of GSK3β was increased." (PMID 35468745, 2022).
oral cancer (19 papers, 2010 to 2025). "A recent study revealed a significant association between oral cancer risk and variants in GSK3β (rs9879992) and WNT11 (rs1533767), which are also associated with NSOC risk." (PMID 32143304, 2020). "Therefore, although targeting each of these pathways has a modest impact on oral cancer and causes toxicity to the patient, targeting GSK3β directly may be highly beneficial in treating OSCC." (PMID 20537194, 2010). "Crosstalk between the Raf-MEK-ERK and PI3K-Akt-GSK3β signaling networks promotes chemoresistance, invasion/migration and stemness in oral cancer." (PMID 36755314, 2023). "Here, we show that nimbolide negatively regulates activation of PI3K/Akt in oral cancer cells by inhibiting phosphorylation of Akt at Ser473 with consequent increase in p-GSK3βTyr216, the active form of GSK3β that inhibits autophagy." (PMID 30352996, 2018). "The expression of GSK3β was significantly higher relative to GSK3α indicating the greater role of the β isoform in oral cancer." (PMID 25645517, 2015). "For instance, the progressive inactivation of GSK-3β was observed in oral carcinoma, with a positive correlation between the expression of pS9GSK-3β and cyclin D1." (PMID 26418031, 2015). "If the activated form of GSK3β is non-toxic to normal oral epithelial cells, as was found in animal models, then the manipulation of the activated GSK3β provides hope for treating oral cancer." (PMID 20537194, 2010). "A recent report suggests that activating GSK3β can reverse the epithelial-mesenchymal process in oral cancer." (PMID 20537194, 2010). "The focus of this review is to discuss the multitude of roles of GSK3β, its possible role in controlling different oncogenic events and how it can be targeted in oral cancer." (PMID 20537194, 2010). "The transcriptional activation of MMP-1,-3, and -9 is common in OSCC, and they are all targets of AP-1, NFκB, C/EBPs or Snail, highlighting the importance of GSK3β-mediated signaling in the oral cancer invasion program." (PMID 20537194, 2010). "This review attempts to correlate the established pathways of oral cancer with GSK3β signaling and discusses the potential of this kinase as a therapeutic target." (PMID 20537194, 2010). "The activation of established GSK3-inactivating upstream biological pathways by oral cancer-predisposing factors, such as tobacco, alcohol, and HPV, support the proposition of a causative role for GSK3β in OSCC." (PMID 20537194, 2010). "GSK3β is a Ser/Thr protein kinase, and there is emerging evidence that it is a tumor suppressor in oral cancer." (PMID 20537194, 2010). "In spite of all this evidence, a detailed analysis of the role of GSK3β in oral cancer and of its therapeutic potential has yet to be conducted by the scientific community." (PMID 20537194, 2010). "Altogether, our study findings preliminarily demonstrate that CTD inhibits proliferation and induces apoptosis of human oral cancer cells by targeting AKT to downregulate the expression of GSK3β, mTOR and TOPK, thus inhibiting cell growth, migration and apoptosis." (PMID 34299129, 2021). "Therefore, the miR-34a-5p/AXL axis promotes the proliferation, metastasis, and EMT of oral cancer cells through the AKT/glycogen synthase kinase (GSK)-3β (GSK-3β)/β-catenin/SNAI1 signaling cascade." (PMID 33917482, 2021). "Therefore, AKT, mTOR and GSK3β at the process of carcinogenesis were appreciated as target molecules for the prevention and treatment of oral cancer." (PMID 34644781, 2021). "There is emerging evidence that glycogen synthase kinase (GSK)3β may be a tumor suppressor in oral cancer." (PMID 25936657, 2015). "In the present study, we found that GSK3β expression plays a key role in oral cancer." (PMID 25645517, 2015). "The data suggest that the inactivation of GSK3, especially GSK3β, might be related to oral cancer progression and might fuel the transcription of cyclin D1." (PMID 25645517, 2015).